HPF1 (histone PARylation factor 1)
Description:
Cofactor for serine ADP-ribosylation that confers serine specificity on PARP1 and PARP2 and plays a key role in DNA damage response. Initiates the repair of double-strand DNA breaks: recruited to DNA damage sites by PARP1 and PARP2 and switches the amino acid specificity of PARP1 and PARP2 from aspartate or glutamate to serine residues, licensing serine ADP-ribosylation of target proteins. Serine ADP-ribosylation of target proteins, such as histones, promotes decompaction of chromatin and the recruitment of repair factors leading to the reparation of DNA strand breaks. Serine ADP-ribosylation of proteins constitutes the primary form of ADP-ribosylation of proteins in response to DNA damage. HPF1 acts by completing the active site of PARP1 and PARP2: forms a composite active site composed of residues from HPF1 and PARP1 or PARP2. While HPF1 promotes the initiation of serine ADP-ribosylation, it restricts the polymerase activity of PARP1 and PARP2 in order to limit the length of poly-ADP-ribose chains. HPF1 also promotes tyrosine ADP-ribosylation, probably by conferring tyrosine specificity on PARP1.
Synonyms: C4orf27; FLJ20534
Tractability: Small molecule: a structure with a bound ligand is known. PROTAC: ubiquitination databases record sites on it.
Gene: Protein-coding gene on chromosome 4 (169,729,468 to 169,757,944, reverse strand). Ensembl gene ENSG00000056050.
Subcellular location: Chromosome; Nucleus
Subcellular location (Human Protein Atlas): Cytosol; Cytokinetic bridge; Microtubules
Gene Ontology:
Molecular function: chromatin binding; histone binding; protein ADP-ribosyltransferase-substrate adaptor activity; protein binding; poly-ADP-D-ribose binding
Biological process: DNA damage response; DNA repair; DNA repair-dependent chromatin remodeling; double-strand break repair; regulation of protein ADP-ribosylation
Cellular component: chromatin; chromosome; nucleus; site of DNA damage
Genetic constraint (gnomAD): Loss-of-function variants: 16 observed, 18.39 expected, observed/expected ratio (o/e) 0.87, 90% interval 0.59 to 1.32. The upper end of that interval is the gene's LOEUF score, 1.32, which puts it in group 5 of 6, group 1 being the genes least tolerant of losing a copy. Missense variants: 216 observed, 218.42 expected, observed/expected ratio (o/e) 0.99, 90% interval 0.88 to 1.11. Synonymous variants: 74 observed, 77.75 expected, observed/expected ratio (o/e) 0.95, 90% interval 0.79 to 1.15.
Homologues: Orthologues: chimpanzee HPF1 (99% identical), macaque HPF1 (97% identical), rabbit HPF1 (91% identical), dog HPF1 (90% identical), mouse Hpf1 (89% identical), rat Hpf1 (88% identical), pig HPF1 (86% identical), zebrafish hpf1 (63% identical), Drosophila melanogaster Hpf1 (37% identical), Caenorhabditis elegans JC8.7 (25% identical).
Diseases named in the same sentence as HPF1 in open-access papers:
HPF1 is named in the same sentence as 7 diseases in open-access papers, as found by Europe PMC text mining. Sharing a sentence is not in itself a finding about the gene and the disease. The quoted sentences say what the papers report.
colorectal cancer (1 paper, 2024). A primary or metastatic malignant neoplasm that affects the colon or rectum. "ANP32B may alter the sensitivity of colorectal cancer cells to PARP1 inhibitor via a mechanism associated with the HPF1 gene." (PMID 38192816, 2024). "RNA sequencing analysis of differentially expressed genes in ANP32B silenced colorectal cancer cells showed that histone PARylation factor 1 (HPF1), which protects against DNA damage by interacting with the anti-tumor target PARP1, was significantly downregulated." (PMID 38192816, 2024). "•ANP32B promotes the progression of colorectal cancer by up-regulating HPF1." (PMID 38192816, 2024). "Targeting the ANP32B/HPF1 axis may have benefit for patients with colorectal cancer." (PMID 38192816, 2024). "Analysis of colorectal cancer samples from The Cancer Genome Atlas showed that ANP32B and HPF1 expression were positively correlated, and recovery assays showed that ANP32B promoted colorectal cancer progression by up-regulating HPF1." (PMID 38192816, 2024).
glioma (1 paper, 2024). A benign or malignant brain and spinal cord tumor that arises from glial cells (astrocytes, oligodendrocytes, ependymal cells). "First, we only explored the effect of ANP32B/HPF1 axis on malignant phenotype of glioma from in vitro experiments, without further verification in vivo." (PMID 38192816, 2024).
osteosarcoma (1 paper, 2022). A usually aggressive malignant bone-forming mesenchymal neoplasm, predominantly affecting adolescents and young adults. "Human osteosarcoma U2OS cells lacking either HPF1 or ARH3 showed opposite responses upon H2O2-induced oxidative stress, i.e., ARH3-knockout cells accumulated ADP-ribosylated serine, whereas HPF1-knockout cells showed decreased serine ADP-ribosylation levels." (PMID 36497109, 2022).
cancer (8 papers, 2021 to 2023). A tumor composed of atypical neoplastic, often pleomorphic cells that invade other tissues. "As such, HPF1 loss could be considered a potential biomarker for cancer therapy." (PMID 34869334, 2021). "From the top 20 genes correlated with FRG1 across cancer types, we found that three genes (HPF1, RPL34, and EXOSC9) were common." (PMID 34795329, 2021). "HPF1, RPL34, and EXOSC9 were the most common genes present in FRG1 associated pathways across the cancer types." (PMID 34795329, 2021). "Similarly, ARH3 also emerges as a potential cancer biomarker and drug target, partially due to being the “opposing force” to HPF1." (PMID 34869334, 2021). "This suggests that a correct dosage of HPF1 is important for proper balancing of various PARP1- and PARP2-catalysed reactions, and therefore subtler changes beyond simple loss-of-function might also be of therapeutic relevance in both cancer and other diseases." (PMID 34210965, 2021). "Based on our data, we propose that inhibitors should be tailored to the PARP1 – HPF1 pair instead of just PARP1 and may result in higher selectivity for inhibition of PARP1 in the DNA-damage response, and thus for cancer treatment." (PMID 33531508, 2021).
tumor (4 papers, 2021 to 2024). "From feature analysis we concluded that collagens, MACROH2A1, HPF1, COL4A3, TBB2C, actin, and H2B are promising targets for the understanding of tumor progression and development of distant metastases, and consequently inspiring novel treatment of PDAC metastatic lesions." (PMID 35956764, 2022).
HPF1 also shares sentences with these, for which no sentence is quoted: Fanconi anemia (1 paper); osteoarthritis (1).